OR5K3 (olfactory receptor family 5 subfamily K member 3)
Description:
Odorant receptor.
Tractability: Antibody: UniProt places it where antibodies can reach, with medium confidence; UniProt predicts a signal peptide or a membrane-spanning region; its Gene Ontology location is reachable by antibodies, with medium confidence.
Gene: Protein-coding gene on chromosome 3 (98,390,666 to 98,391,631, forward strand). Ensembl gene ENSG00000206536.
Subcellular location: Cell membrane
Pathways (Reactome):
Sensory Perception: Expression and translocation of olfactory receptors
Gene Ontology:
Molecular function: odorant binding; olfactory receptor activity; G protein-coupled receptor activity
Biological process: sensory perception of smell; detection of chemical stimulus involved in sensory perception of smell; G protein-coupled receptor signaling pathway
Cellular component: plasma membrane; membrane
Genetic constraint (gnomAD): Missense variants: 369 observed, 300.52 expected, observed/expected ratio (o/e) 1.23, 90% interval 1.13 to 1.34. Synonymous variants: 133 observed, 106.01 expected, observed/expected ratio (o/e) 1.25, 90% interval 1.09 to 1.45.
Homologues: Orthologues: chimpanzee OR5K3 (97% identical), rabbit OR5K3 (86% identical), rat Or5k3 (78% identical), mouse Or5k3 (77% identical), mouse Or5k14 (76% identical), rat Or5k14 (75% identical), rat Or5k8 (75% identical), dog OR5K18 (74% identical), rat Olr1563 (74% identical), rat Olr1564 (74% identical), mouse Or5k8 (73% identical), dog OR5K6 (73% identical), and 2 more. Paralogues in human: OR5K4 (74% identical), OR5K1 (71% identical), OR5K2 (69% identical), OR5H2 (50% identical), OR5H1 (48% identical), OR5AC2 (47% identical), OR5H6 (47% identical), OR5H14 (47% identical), OR5H15 (47% identical), OR9H1 (45% identical), OR5B12 (45% identical), OR5I1 (45% identical), and 84 more.